C11orf86 (chromosome 11 open reading frame 86)
Synonyms: FLJ22675; FACI
Tractability: No criterion of Open Targets' tractability assessment is met for any kind of drug.
Gene: Protein-coding gene on chromosome 11 (66,975,277 to 66,977,009, forward strand). Ensembl gene ENSG00000173237.
Genetic constraint (gnomAD): Loss-of-function variants: 17 observed, 15.56 expected, observed/expected ratio (o/e) 1.09, 90% interval 0.75 to 1.62. The upper end of that interval is the gene's LOEUF score, 1.62, which puts it in group 6 of 6, group 1 being the genes least tolerant of losing a copy. Missense variants: 144 observed, 149.67 expected, observed/expected ratio (o/e) 0.96, 90% interval 0.84 to 1.11. Synonymous variants: 86 observed, 66.04 expected, observed/expected ratio (o/e) 1.3, 90% interval 1.09 to 1.56.
Homologues: Orthologues: chimpanzee C11H11orf86 (99% identical), macaque C14H11orf86 (89% identical), rat C1h11orf86 (74% identical), mouse 2010003K11Rik (72% identical), pig C11orf86 (68% identical), dog C11orf86 (67% identical), guinea pig C11orf86 (64% identical).
Diseases named in the same sentence as C11orf86 in open-access papers:
C11orf86 is named in the same sentence as 5 diseases in open-access papers, as found by Europe PMC text mining. Sharing a sentence is not in itself a finding about the gene and the disease. The quoted sentences say what the papers report.
colon cancer (1 paper, 2020). "The TCGA results indicated that SPIB, KRT24, PHLPP2, PLP1, BEST4, CA7, and C11orf86 were all downregulated, while KRT80, SLC39A10, AJUBA, FOXQ1, and CLDN1 exhibited upregulated levels in colon cancer." (PMID 32633726, 2020).
C11orf86 also shares sentences with these, for which no sentence is quoted: cancer (2 papers); dyslipidemia (1); Hypercholesterolemia (1); tumor (1).